IL17RD (interleukin 17 receptor D)
Description:
Feedback inhibitor of fibroblast growth factor mediated Ras-MAPK signaling and ERK activation. Regulates the nuclear ERK signaling pathway by spatially blocking nuclear translocation of activated ERK without inhibiting cytoplasmic phosphorylation of ERK. Mediates JNK activation and may be involved in apoptosis (By similarity). May inhibit FGF-induced FGFR1 tyrosine phosphorylation (By similarity). Might have a role in the early stages of fate specification of GnRH-secreting neurons (By similarity). Inhibits TGFB-induced epithelial-to-mesenchymal transition in lens epithelial cells (By similarity).
Synonyms: IL-17RD; IL17RLM; SEF; FLJ35755; HH18
Tractability: Antibody: UniProt places it where antibodies can reach, with high confidence; UniProt predicts a signal peptide or a membrane-spanning region; its Gene Ontology location is reachable by antibodies, with medium confidence.
Gene: Protein-coding gene on chromosome 3 (57,089,982 to 57,170,306, reverse strand). Ensembl gene ENSG00000144730.
Subcellular location: Golgi apparatus membrane; Cell membrane; Cytoplasm (Isoform 4)
Subcellular location (Human Protein Atlas): Golgi apparatus; Nucleoplasm
Pathways (Reactome):
Signal Transduction: MAP2K and MAPK activation
Gene Ontology:
Molecular function: protein binding; interleukin-17 receptor activity
Biological process: interleukin-17-mediated signaling pathway; negative regulation of epithelial to mesenchymal transition; negative regulation of transforming growth factor beta receptor signaling pathway
Cellular component: Golgi apparatus; Golgi membrane; plasma membrane; cytoplasm
Genetic constraint (gnomAD): Loss-of-function variants: 43 observed, 58.27 expected, observed/expected ratio (o/e) 0.74, 90% interval 0.58 to 0.95. The upper end of that interval is the gene's LOEUF score, 0.95, which puts it in group 4 of 6, group 1 being the genes least tolerant of losing a copy. Missense variants: 856 observed, 804.59 expected, observed/expected ratio (o/e) 1.06, 90% interval 1 to 1.13. Synonymous variants: 349 observed, 329 expected, observed/expected ratio (o/e) 1.06, 90% interval 0.97 to 1.16.
Homologues: Orthologues: chimpanzee IL17RD (99% identical), macaque IL17RD (99% identical), rabbit IL17RD (93% identical), pig IL17RD (90% identical), dog IL17RD (90% identical), guinea pig IL17RD (89% identical), rat Il17rd (88% identical), mouse Il17rd (87% identical), tropical clawed frog il17rd (62% identical), zebrafish il17rd (51% identical). Paralogues in human: IL17RA (19% identical), IL17RB (12% identical), IL17RC (10% identical), IL17RE (9% identical).